ANKRD12 (ankyrin repeat domain 12)
Description:
May recruit HDACs to the p160 coactivators/nuclear receptor complex to inhibit ligand-dependent transactivation.
Synonyms: KIAA0874; FLJ20053; GAC-1; ANCO-2; ANCO1; Nbla00144
Tractability: PROTAC: ubiquitination databases record sites on it; its protein half-life has been measured.
Gene: Protein-coding gene on chromosome 18 (9,136,228 to 9,285,985, forward strand). Ensembl gene ENSG00000101745.
Subcellular location: Nucleus
Subcellular location (Human Protein Atlas): Nucleoplasm; Cytosol
Gene Ontology:
Cellular component: nucleoplasm; nucleus
Genetic constraint (gnomAD): Loss-of-function variants: 79 observed, 163.36 expected, observed/expected ratio (o/e) 0.48, 90% interval 0.4 to 0.58. The upper end of that interval is the gene's LOEUF score, 0.58, which puts it in group 2 of 6, group 1 being the genes least tolerant of losing a copy. Missense variants: 2,294 observed, 2,274.6 expected, observed/expected ratio (o/e) 1.01, 90% interval 0.97 to 1.04. Synonymous variants: 866 observed, 774.59 expected, observed/expected ratio (o/e) 1.12, 90% interval 1.06 to 1.18.
Homologues: Orthologues: chimpanzee ANKRD12 (99% identical), macaque ANKRD12 (98% identical), dog ANKRD12 (90% identical), pig ANKRD12 (89% identical), rabbit ANKRD12 (89% identical), guinea pig ANKRD12 (87% identical), mouse Ankrd12 (81% identical), rat Ankrd12 (80% identical), tropical clawed frog ankrd12 (57% identical), zebrafish ankrd12 (47% identical).
Diseases named in the same sentence as ANKRD12 in open-access papers:
ANKRD12 is named in the same sentence as 21 diseases in open-access papers, as found by Europe PMC text mining. Sharing a sentence is not in itself a finding about the gene and the disease. The quoted sentences say what the papers report.
colorectal cancer (5 papers, 2013 to 2021). A primary or metastatic malignant neoplasm that affects the colon or rectum. "A previous report showed that ANKRD12 was downregulated in colorectal cancer and that lower expression correlated with poor survival and liver metastasis in colorectal cancer patients." (PMID 33107222, 2021). "Previous reports have shown that ANKRD12 gene expression is correlated with metastasis and poor survival of colorectal cancer patients." (PMID 33632317, 2021). "A clinical study of gene expression of ANKRD12 in colorectal cancer revealed that low ANKRD12 expression is correlated with overall poor survival and liver metastasis of CRC patients." (PMID 31185953, 2019). "The precise molecular mechanisms behind the altered expression of ANKRD12 in colorectal cancer are unclear." (PMID 23718802, 2013). "The aim of this study was to investigate the ANKRD12 mRNA expression in colorectal cancer (CRC) tumor tissues and the normal adjacent mucosa and its potential relevance to clinicopathological characteristics and prognosis." (PMID 23718802, 2013). "Low ANKRD12 level is an independent prognostic predictor of colorectal carcinoma patients." (PMID 31185953, 2019).
breast carcinoma (2 papers, 2019 to 2022). "In this study, we identified and characterized circular RNA isoforms from ANKRD12 gene (circANKRD12) that are abundantly expressed in ovarian and breast cancer cells." (PMID 31185953, 2019). "Oncogenic genes like FAM83D, CTDSP1, and SAPCD2 were downregulated in all three cells, and tumor suppressor genes (TSGs) like ZNF292, ANKRD12, NKAPL, and CCL21 were upregulated in all three breast cancer cells upon curcumin treatment." (PMID 34981672, 2022).
Diabetes (2 papers, 2022 to 2024). "For the two rare-variant genes (GIGYF1 and ANKRD12) associated with alcohol consumption, GIGYF1, identified as a risk gene for diabetes in earlier research, is a protein-coding gene intricately involved in the regulation of cell growth and division." (PMID 38982111, 2024). "ANKRD12, NME7 and REV1 showed a 1.6 to 2.5-fold decreased expression in kidney glomeruli from individuals with DKD compared to healthy living donors (p < 0.01) in the Woroniecka Diabetes Dataset21." (PMID 36550108, 2022).
Obesity (2 papers, 2022 to 2024). Accumulation of substantial excess body fat. "Reports have already shown that ANKRD12, NEXN, IFT74, and ROCK1 play an important role in adipose deposition or obesity." (PMID 38474122, 2024). "Among these genes, AHI1, AKAP9, ANKRD12, CCDC18, IFT74, NEXN, etc., have been shown to play an important role in adipose deposition or obesity." (PMID 38474122, 2024).
bronchitis (1 paper, 2022). An acute or chronic inflammatory process affecting the bronchi. "We observed pleiotropic effects of ANKRD12 pLOF which associated with a range of diverse traits including total protein, blood cell counts, performance on cognitive tests, and bronchitis." (PMID 35896531, 2022).
Dysarthria (1 paper, 2023). Dysarthric speech is a general description referring to a neurological speech disorder characterized by poor articulation. "For instance, ANKRD12 was associated with both EDU and VNR in our exome-wide PTV burden association tests; it is also associated with dysarthria and anarthria, myasthenia gravis and disorders of calcium metabolism in our PTV burden PheWAS." (PMID 37231097, 2023).
dyslexia (1 paper, 2016). A learning disorder characterized by an impairment in processing written words. "ANKRD12 is located within a dyslexia candidate region, DYX6, on 18p11.22." (PMID 27120335, 2016).
Intellectual disability (1 paper, 2024). "Moreover, ANKRD12 and GIGYF1 are well-known genes for reduced cognitive function and intellectual disability as evidenced by previous studies." (PMID 38982111, 2024).
lung carcinoma (1 paper, 2019). "Ovarian cancer cell lines show a higher abundance of ANKRD12 circRNA compared to breast and lung cancer cell lines." (PMID 31185953, 2019).
lymph node metastasis (1 paper, 2013). "Univariate analysis with Cox proportional hazards model identified four prognostic factors: location, lymph node metastasis, liver metastasis, and ANKRD12 expression." (PMID 23718802, 2013).
myocardial infarction (1 paper, 2023). Gross necrosis of the myocardium, as a result of interruption of the blood supply to the area, as in coronary thrombosis. "Regarding myocardial infarction, a study of high-throughput RNA sequencing found that 3,862 circRNAs are dysregulated in peripheral blood, and the differentially expressed circ-TMEM165, circ-UBAC2, circ-ZNF609, circ-ANKRD12, and circ-SLC8A1 are confirmed in the AC16 cell model." (PMID 37840751, 2023).
schizophrenia (1 paper, 2019). A major psychotic disorder characterized by abnormalities in the perception or expression of reality. "More definite mechanisms influencing the increase of ANKRD12 concentration in serum of patients with schizophrenia required clarification." (PMID 31291891, 2019). "Significant difference between three groups was revealed in ANKRD12 concentration (p = 0.02), with maximum elevation of ANKRD12 concentration (median level) in schizophrenia." (PMID 31291891, 2019). "Significant difference between three groups was revealed in ANKRD12 concentration (p = 0.02), with maximum elevation of ANKRD12 concentration (median level) in schizophrenia followed by BD." (PMID 31291891, 2019).
cancer (6 papers, 2012 to 2022). A tumor composed of atypical neoplastic, often pleomorphic cells that invade other tissues. "Circular isoforms of ANKRD12 have been identified in cancer cells and patient samples in many recent studies including ours." (PMID 31185953, 2019). "In the present study, we investigated the functional role of a high abundance circRNA from Ankyrin Repeat Domain 12 (ANKRD12) gene in cancer progression." (PMID 31185953, 2019). "By qRT-PCR, we showed that ANKRD12 expression in cancer tissues were significantly lower ( P < 0.001) than those in the normal adjacent mucosa." (PMID 23718802, 2013). "Furthermore, the ANKRD12 circRNA modulates the invasiveness of cancer cells, but little is known about the role of circRNAs derived from the ANKRD12 gene in BMSC differentiation and OP." (PMID 33632317, 2021). "(c) The abundance of circANKRD12 and ANKRD12 mRNA in a panel of cancer cells." (PMID 31185953, 2019). "However, the clinical significance of ANKRD12 expression in cancer remains unclear." (PMID 23718802, 2013). "Moreover, focal CNA amplifications encompassed genomic peaks that harbored canonical cancer genes including those found at HPV-integrated hotspots (MYC, MYCN, MYCL, SOX2, NR4A2, and ANKRD12), and others (CCNE1, SMAD2, BCL2L1, and GNAS)." (PMID 36216793, 2022).
tumor (3 papers, 2013 to 2022). "We also analyzed the common downregulated genes and found that many of these genes such as ANKRD12, KIAA1551, and APC encode proteins with tumor suppressive functions." (PMID 30993034, 2019). "In conclusion, we found that ANKRD12 mRNA were downregulated in CRC tumor tissues and low ANKRD12 mRNA expression correlated with poor overall survival and liver metastasis of CRC patients." (PMID 23718802, 2013). "The relative mRNA expression of ANKRD12 were significantly lower in CRC tumor tissues than in the normal adjacent mucosa (P < 0.001), and the cases with low ANKRD12 expression showed a higher frequency of liver metastasis (P = 0.015)." (PMID 23718802, 2013). "This study revealed that ANKRD12 mRNA were down regulated in CRC tumor tissues and low ANKRD12 expression was correlated with liver metastasis and poor survival of CRC patients." (PMID 23718802, 2013). "However, the precise role of ANKRD12 in transcriptional regulation and tumor process is less clear." (PMID 23718802, 2013). "The ANKRD12 mRNA expression was not related to age, gender, histological type, depth of invasion(T), lymph node metastasis, tumor location." (PMID 23718802, 2013).
ANKRD12 also shares sentences with these, for which no sentence is quoted: Autoimmunity (1 paper); esophageal squamous cell carcinoma (1); myasthenia gravis (1); neurodegenerative disease (1); ovarian carcinoma (1); thyroid disease (1); type 2 diabetes (1).